CCND1 (cyclin D1)
Diseases named in the same sentence as CCND1 in open-access papers (continued):
Sharing a sentence is not in itself a finding about the gene and the disease.
leprosy (1 paper, 2020). Leprosy is a chronic infectious disease affecting primarily the skin and peripheral nervous system. "We therefore decided to evaluate the expression of cyclin D1 in the dermal nerves of a subsample of 10 leprosy and five non-leprosy samples." (PMID 32265900, 2020). "When determining the lack of overexpression of Notch components in dermal nerve fibers in leprosy patients, it was feasible that the neural damage model was not related to cyclin D1 expression." (PMID 32265900, 2020). "With regard to the expression of cyclin D1 in the nerve fibers, 100% (n = 10) of leprosy samples showed no cyclin expression in the evaluated dermal nerves." (PMID 32265900, 2020).
Leydig cell cancer (1 paper, 2018). "This would result in cell proliferation in Leydig cell cancer, or magnify cyclin D1 concentration inducing breast cell proliferation." (PMID 29721213, 2018).
liver failure (1 paper, 2019). A liver disease characterized by the liver losing or has lost all of its function. "This prevents Cyclin D1 from initiating cell cycle progression resulting in severe liver failure or delayed recovery." (PMID 31034519, 2019).
liver tumor (1 paper, 2023). "By binding to the lymphoid enhancer factor (LEF)/T-cell factor (TCF) family of DNA binding proteins, CTNNB1 enters the nucleus and regulates transcription of target genes such as c-mycor cyclin D1, resulting in proliferation and metastasis of liver tumor cells." (PMID 37733676, 2023).
lung adenoma (1 paper, 2010). A benign, well circumscribed epithelial neoplasm that arises from the bronchus or the lung parenchyma. "We also assessed the protein levels of the cell cycle marker, cyclin D1 in the same tissue and cells because it was up-regulated in the MDA-F471 cells at the mRNA level and was previously shown to display intensive expression in lung adenomas and adenocarcinomas from mice exposed to NNK." (PMID 20686609, 2010).
lung disease (1 paper, 2021). "There are lines of evidence on the role of CCND1 encoding cyclin D1 in PASMCs and pulmonary vascular remodeling, especially in Group 3 PH (PH associated with hypoxia and lung disease)." (PMID 34977488, 2021).
lung giant cell carcinoma (1 paper, 2021). A morphologic variant of lung sarcomatoid carcinoma characterized by the presence of mononuclear and multinucleated pleomorphic neoplastic giant cells that lack cohesion. "BBR inhibits AP‐1 signaling pathway activity and reduces the binding of transcription factors to the CCND1 AP‐1 motifs, which is an essential mechanism for the action of berberine as a cyclin‐D1 regulator against human lung giant cell carcinoma." (PMID 33650320, 2021).
mesoblastic nephroma (1 paper, 2019). A solid, unencapsulated tumor of the kidney composed of spindle mesenchymal cells that resemble fibroblasts or muscle cells. "Out of 4 cases of congenital mesoblastic nephroma, 3 were cellular type and 1 was of mixed type and all demonstrated reactivity for Cyclin D1." (PMID 30736802, 2019).
minimal change disease (1 paper, 2024). "Second, while elevated expression of CCND1 and CAPD2 has been noted in MN glomerular podocytes, their roles in other podocytopathies like minimal change disease are yet to be defined." (PMID 38846934, 2024).
Miscarriage (1 paper, 2023). A pregnancy that ends at a stage in which the fetus is incapable of surviving on its own, defined as the spontaneous loss of a fetus before the 22th week of pregnancy. "Other studies have reported a substantial decrease in trophoblast cell numbers in early RSA patients, along with down-regulation of STAT3 and its downstream target genes cyclin D1 (CCND1) and vascular endothelial growth factor A (VEGF) in miscarriage tissues (chorionic villi and decidua)." (PMID 38235138, 2023).
monocytic leukemia (1 paper, 2010). "We found that celastrol could arrest human monocytic leukemia cells U937 at G0/G1 phase, this arrest accompanied by down-regulation of Cyclin D1, Cdk4, Cdk6, and Cdk2." (PMID 20398364, 2010).
mouth cancer (1 paper, 2007). "Cyclin D1 expression was measured and the association between such substance and metastasis was found in 45 patients with mouth cancer treated by the author of this paper." (PMID 17505605, 2007).
mucinous ovarian carcinomas (1 paper, 2025). An invasive malignant neoplasm that arises from the ovary and is characterized by the presence of malignant epithelial cells that contain intracytoplasmic mucin and may resemble the epithelial cells of the endocervix or gastrointestinal tract. "Analyses of focal copy number changes revealed amplifications of CCND1 and ERBB2 and homozygous deletions of CDKN2A/B in mucinous ovarian carcinomas, a finding consistent with previous studies." (PMID 40981433, 2025).
mucinous tumour (1 paper, 2013).
muscle tumor (1 paper, 2025). "Targeting CCDN1 to CCND1 blocks cell cycle progression and promotes apoptosis in uterine smooth muscle tumor cells." (PMID 40336816, 2025).
myelofibrosis (1 paper, 2014). A partial or complete replacement of the bone marrow stroma by fibrous tissue. "Importantly, we found that the cyclin D gene (CCND1) was significantly upregulated in MPNs, being most deregulated in myelofibrosis similar to Nrf2." (PMID 25397683, 2014).
myoepitheliomas (1 paper, 2011). "By using fluorescence in situ hybridization for CCND1 and FUS, respectively, no breaks in these genes could be detected in chondroid lipoma or in myoepithelioma." (PMID 21559269, 2011).
myxoid liposarcoma (1 paper, 2011). A liposarcoma characterized by the presence of round non-lipogenic primitive mesenchymal cells and small signet ring lipoblasts within a myxoid stoma with a branching vascular pattern. "Therefore, CCND1 could be used for distinction between myxoid liposarcoma and chondroid lipoma: 4/4 (100%) positivity in chondroid lipoma and 0/18 (0%) positivity in myxoid liposarcoma." (PMID 21559269, 2011). "Especially immunohistochemistry for CCND1 and FISH analysis for the specific translocations may be supportive to discriminate between myxoid liposarcoma and chondroid lipoma." (PMID 21559269, 2011). "None of the 18 myxoid liposarcomas showed immunohistochemically CCND1 expression." (PMID 21559269, 2011).
nasopharynx cancer (1 paper, 2019). "Radiotherapy of nasopharynx cancer patients may induce the observably alteration of lncRNAs especially lncRNA AK294004, a negative regulator of CCND1, which participate in the process of cancer resistance." (PMID 31602253, 2019).
neurofibromatosis (1 paper, 2018). A hereditary neoplastic syndrome in which tumors grow in the nervous system.
nevus (1 paper, 2022). Nevus (or naevus, plural nevi or naevi, from nævus, Latin for "birthmark") is the medical term for sharply circumscribed[1] and chronic lesions of the skin or mucosa. "Mutations of the β-catenin pathway have been reported to transform the phenotype of a BRAF-mutated common nevus into that of a deep penetrating nevus, including increased pigmentation, cell volume, and cyclin D1 levels in the nucleus." (PMID 36077603, 2022).
NK/T-cell lymphoma (1 paper, 2021). "In NK/T-cell lymphoma, EZH2 directly activates CCND1 transcription independent of methyltransferase activity." (PMID 34376807, 2021).
non-cutaneous melanoma (1 paper, 2022). Melanoma is a malignant tumor of melanocytes, cells that are derived from the neural crest. "In a review of CCND1 copy number variation in metastatic non-cutaneous melanoma, amplification was prominent in those patients whose disease did not respond to immune checkpoint inhibition." (PMID 35982973, 2022).
ocular adnexal lymphoma (1 paper, 2013). A non-Hodgkin lymphoma arising from the conjunctiva, lacrimal gland, lacrimal drainage apparatus, eyelids, or other orbital tissues around the eye. "However, CD5 and cyclin D1 are two markers that can lead to diagnostic pitfalls that could drastically impact patient care within the realm of orbital and ocular adnexal lymphomas." (PMID 23691402, 2013).
oral epithelial dysplasia (1 paper, 2022). "The present study aimed to examine the KRAS expression in oral epithelial dysplasia and squamous cell carcinoma of the oral cavity and to correlate its expression with the established prognostic markers (Ki-67, bcl2, and Cyclin D1) and the available clinicopathologic factors." (PMID 36532636, 2022). "The paraffin-embedded tissue was analyzed for the expression of KRAS for oral epithelial dysplasia and OSCC, and ki-67, Cyclin D1, and bcl2 were analyzed only for OSCC." (PMID 36532636, 2022).
oropharyngeal tumors (1 paper, 2024). "In breast and oropharyngeal tumors, the positive expression of cyclin D1 was associated with lower disease-free survival." (PMID 38742684, 2024).
ovarian disease (1 paper, 1997). "In the current study, the expression of cyclin D1 has been investigated in a series of 33 patients, with benign (10 patients), borderline (five patients) and malignant (18 patients) ovarian disease." (PMID 9155044, 1997).
papillary adenocarcinoma (1 paper, 2024). A morphologic variant of adenocarcinoma.
parasitic infection (1 paper, 2012). "Up-regulation of PCNA, Cyclin D1, A and B1 is related to the regulation of the G1/S and G2/M phases, which were previously reported to increase biphasically after partial hepatectomy and other parasitic infection." (PMID 22253905, 2012).
parathyroid disease (1 paper, 2022). "Paralleling animal experiments, high levels of cyclin D1 protein have been reported in human multiglandular parathyroid disease in the setting of primary hyperparathyroidism." (PMID 35805976, 2022).
Peripheral T-cell lymphomas (1 paper, 2012). "Here we report a case of Peripheral T-cell lymphomas Not Otherwise Specified with cyclin D1 gene copy gain associated with protein overexpression." (PMID 22770229, 2012). "In this paper we described a case of peripheral T cell lymphoma with atypical expression of cyclin D1." (PMID 22770229, 2012). "A peripheral T cell lymphoma, unspecified, was diagnosed, according to the morphology and immunophenotype, with unusual cyclin D1 expression." (PMID 22770229, 2012). "In this short report we show overexpression of cyclin D1 in a peripheral T-cell lymphoma." (PMID 22770229, 2012). "On the contrary cyclin D1 overexpression, to the best of our knowledge, has not been hitherto described in nodal Peripheral T-cell lymphomas, Not Otherwise Specified." (PMID 22770229, 2012).
pharyngeal cancer (1 paper, 2023). "Activation of the Akt/GSK-3β/cyclin D1 pathway, leading to the proliferation of pharyngeal cancer cells." (PMID 36908412, 2023).
phyllodes tumor (1 paper, 2024). A benign, borderline, or malignant fibroepithelial neoplasm arising from the breast and rarely the prostate gland. "IHC may show expression of CD10, but phyllodes tumors generally express CD34 and B-cell lymphoma 2 (bcl-2) and do not express cyclin D1." (PMID 39474112, 2024).
pilocytic astrocytoma (1 paper, 2016). Pilocytic astrocytoma is a rare subtype of low-grade glioma of the central nervous system characterized by a well circumscribed, often cystic, brain tumor with a discrete mural nodule and long, hair-like projections that extend from the neoplastic astrocytes. "Further analysis also revealed that a subset of published and predicted targets of AP-1 is up-regulated in pilocytic astrocytomas, including the cyclin D1 gene CCND1." (PMID 27229157, 2016).
pineal tumors (1 paper, 2012).
polycythemia vera (1 paper, 2025). "HHT, a recognized protein synthesis inhibitor, playing a significant role in the treatment of hematological diseases such as AML, CML, MDS, and polycythemia vera by regulating mechanisms including KIT, MYC, MCL-1 and Cyclin-D1." (PMID 40591114, 2025).
posterior fossa ependymoma (1 paper, 2020). A high grade ependymoma that is located within the posterior fossa. "We found that most cell-cycle-related genes were overexpressed in supratentorial and posterior fossa ependymomas, particularly cyclin D1 and CDK4, which can serve as actionable therapeutic targets." (PMID 33271970, 2020).
primary immunodeficiency (1 paper, 2023). "In the present study, we found that CTG, which encodes leucine, was the most preferred codon in APP, CCND1, and PTPA, as well as in genes common to primary immunodeficiency and cancer." (PMID 37383425, 2023).
prolactinoma (1 paper, 2022). "Accordingly, JAK3 and CCND1 showed high expression levels in the M6 prolactinoma, indicating the existence of a proliferating autocrine loop in this tumor." (PMID 35978432, 2022).
prostate (1 paper, 2018). "Cyclin D1 overexpression has been implicated in prostate carcinogenesis and aggravated bone metastasis." (PMID 30555320, 2018).
retinal angiomas (1 paper, 2009). "Subsequently, we reported that a functional variant in the VHL target gene CCND1 influenced risk of retinal angiomas and central nervous system hemangioblastomas (but not RCC) in VHL disease patients." (PMID 19551141, 2009).
Richter syndrome (1 paper, 2023). Transformation of chronic lymphocytic leukemia into aggressive non-Hodgkin's lymphoma, usually diffuse large B-cell lymphoma (immunoblastic or centroblastic variant). "Therefore, it is recommended to routinely examine CD5 and Cyclin D1 for the differential diagnosis of DLBCL, blastoid/pleomorphic variant MCL, DLBCL-type Richter syndrome and primary CD5-positive DLBCL, which is more aggressive." (PMID 37182167, 2023).
rosacea (1 paper, 2021). A chronic erythematous skin disorder that affects the face. "Moreover, studies demonstrated the potential relationship between MLT target genes (MMP9, CCND1, EGFR, ICAM1, PTGS2, and SERPINE1) and rosacea-related key genes (IL-6, IL-1β, IFNγ, IL-17, and TNF-α)." (PMID 34899707, 2021).
Salivary Gland Pleomorphic Adenoma (1 paper, 2022). A benign, slow-growing tumor composed of cells that demonstrate both epithelial and mesenchymal differentiation. "The objective of this retrospective study was to explore possible changes in histopathological features and expression of cyclin D1 and MIB-1 in salivary gland pleomorphic adenomas (PAs) that recur or undergo malignant transformation." (PMID 35637257, 2022).
Salmonella Infections (1 paper, 2024). Infections with bacteria of the genus SALMONELLA. "Our analysis of cyclin D1, D2, B1, and B2 revealed that Salmonella infection in HeLa and HepG2 only affects D1 and B1." (PMID 39201742, 2024).
schwannomatosis (1 paper, 2017). The least frequent form of the rare genetic disorder neurofibromatosis. "A cyclin D1 repression assay has shown that mutant SMARCB1 proteins, derived from expression plasmids harbouring the same missense and splice-site mutations noted in patients with schwannomatosis, were capable of suppressing cyclin D1 activity in a similar manner to the wild-type SMARCB1 protein." (PMID 27921248, 2017).
severe combined immunodeficiency (1 paper, 2016). Severe combined immunodeficiency (SCID) comprises a group of rare monogenic primary immunodeficiency disorders characterized by a lack of functional peripheral T lymphocytes resulting in early-onset severe respiratory infections and failure to thrive. "Furthermore, oncogene activation, such as Cyclin‐D1 and C‐myc, can enhance anchorage‐independent growth of mouse mammary epithelial cells and tumour growth in severe combined immunodeficiency mice." (PMID 27374312, 2016).
skin papilloma (1 paper, 2019). A benign papillary neoplastic growth on the skin composed of epithelial cells and a fibrous stalk. "Corroborating this, murine CYLD-knockout models develop skin papillomas following chemical carcinogenesis that demonstrate increased expression of NF-κB target genes such as cyclin D1 (CCND1) mediated by dysregulation of BCL320." (PMID 31624251, 2019).
Small Intestinal Adenocarcinoma (1 paper, 2023). "The cyclin D1 expression in small intestinal adenocarcinomas (SIACs) has not yet been comprehensively studied, owing to the rarity of this tumor." (PMID 37894399, 2023).
small intestine tumors (1 paper, 2012). "We demonstrated the expressions of ERK5 and its downstream effectors, c-Myc, c-jun and cyclin D1, were also suppressed in the transgenic small intestine tumors." (PMID 22876303, 2012).
steatosis (1 paper, 2019). Increased lipid within the cytoplasm of cells. "Administering GLP1 also caused a rise in the count of PCNA-positive cells and in levels of cyclin D1 and A when compared to grafts from CD donors without treatment in livers with steatosis." (PMID 31835410, 2019).
Ta (1 paper, 2024). "In Ta tumors, the most frequent gene variants were FGFR3 (48%) and PIK3CA (26%), and the most common amplifications were AKT1 (24%), FGFR3 (13%), MYCN (11%), and CCND1 (11%)." (PMID 39410541, 2024). "Our analysis identified two subgroups in Ta tumors: one with FGFR3 alterations linked to LG tumors and favorable outcomes, and another with alterations in ERBB2, PIK3CA, and ERBB3 mutations, and FGFR1, CCND1, and MYC amplifications, associated mostly with HG tumors and poorer prognosis." (PMID 39410541, 2024).
tapeworm infections (1 paper, 2025). "Based on results from proteomics screens we investigated the potential of niclosamide, an FDA-approved anthelmintic drug with a 50 year history in treating tapeworm infections, as a molecular glue degrader targeting the proto-oncogene cyclin D1." (PMID 40337304, 2025).
testicular cancer (1 paper, 2016). A primary or metastatic malignant neoplasm that affects the testis. "Interestingly, CCND1 is overexpressed in cisplatin resistant testicular cancer and OVCA." (PMID 26879975, 2016).
testicular germ cell tumours (1 paper, 2012). "As Cyclin D1 is frequently over expressed in testicular germ cell tumours which have become resistant to cisplatin therapies, we concur with the hypothesis that the high levels of Cyclin D1 cause an accelerated cell cycle transition and limit the cells sensitivity to the chemotherapy agent." (PMID 22536405, 2012).